CHIT1 (chitinase 1)
Diseases named in the same sentence as CHIT1 in open-access papers (continued):
Sharing a sentence is not in itself a finding about the gene and the disease.
infection (15 papers, 2011 to 2025). The state of being infected such as from the introduction of a foreign agent such as serum, vaccine, antigenic substance or organism. "At day 5 (the experimental endpoint due to 20% weight loss in WT mice) after infection with C. albicans, Chit1−/− mice showed minimal weight loss by day 5 post infection compared to WT, 92.3 ± 6.9 vs. 81.5 ± 4.8 %, P < 0.05)." (PMID 33796101, 2021). "This implies that CHIT1 might be associated with infection processes, while CHIT2 could be involved in morphogenesis and cellular growth." (PMID 39493578, 2024). "In this study, we observe that CHIT1 is significantly downregulated in bryozoans during T. bryosalmonae infection, suggesting that chitinase may be closely linked with inflammation and infection progression." (PMID 32824626, 2020). "Consequently, a 24 base pair duplication in the CHIT1 gene (H allele) with high prevalence in European populations is associated with a deficiency in the activity of CHIT1 and is suspected to result in a higher susceptibility to infection." (PMID 34321067, 2021). "In parallel with this, proteins with LysM domains like intracellular hyphae protein-1 (KXH41657), endochitinase (KXH30597), and chitinase-1 (KXH64700) were significantly expressed starting from the early stages of the infection." (PMID 39925370, 2024). "The fungal burden in the kidney was significantly lower in the Chit1−/− mice at day 5 post infection compared to WT, 5.5 ± 1.0 vs. 6.8 ± 0.2 log10 CFUs/gram kidney tissue, P < 0.05)." (PMID 33796101, 2021). "The insect bioassay results displayed that overproduction of the novel endochitinase Chit1 can increase the infection efficiency of M. anisopliae and promote infection against adults of B. tabaci." (PMID 31598241, 2019). "In fact, our data suggest the absence of Chit1 was beneficial as the genetic deficient animals demonstrated nearly a full recovery of infection induced weight loss and decreasedfungal burden." (PMID 33796101, 2021). "The loss of Th2 cell accumulation with Chit1 deficiency was responsible for attenuation of disease, because the use of IL-2 complexes to boost Th2 cell numbers and associated cytokines also hastened lethal disease in Chit1−/− mice compared with infection-matched, untreated Chit1−/− controls." (PMID 25764512, 2015). "Based on these results, increasing CHIT1 activity and the subsequent emergence of diffusible TLR2 ligands during infection over time would mean an increasing contribution of TLR2-dependent immunity to antifungal responses, which have been demonstrated in infection models." (PMID 40098951, 2025).
neurodegenerative disease (13 papers, 2011 to 2025). A disorder of the central nervous system characterized by gradual and progressive loss of neural tissue and neurologic function. "CHIT1, another chitinase expressed by activated macrophages, is elevated in the CSF across several neurodegenerative diseases, including ALS, where it promotes neuroinflammation by activating microglia and astrocytes." (PMID 40305176, 2025). "CHIT1 levels were elevated in the CSF of ALS patients compared to other neurodegenerative diseases (ONDS) control (SMD, 0.74; 95% CI, 0.22 – 1.27; P < 0.001) and exhibited an even more substantial increase when compared to ALS-mimicking diseases (AMDS) (SMD, 1.15; 95% CI, 0.35 – 1.94, P < 0.001)." (PMID 38194198, 2024). "CHIT1 levels in SMA were lower than described for ALS or other neurodegenerative diseases, implying a minor involvement of neuroinflammation in SMA and arguing against the usefulness of CHIT1 as a disease severity biomarker for SMA." (PMID 34321067, 2021). "By analogy with the amyloid-tau-neurodegeneration (A/T/N) classification in neurodegenerative diseases, a similar approach could be considered for mitochondriopathies, including biomarkers for metabolic disturbance (FGF21), apoptosis/cellular stress (GDF15) and lysosomal dysfunction (CHIT1)." (PMID 39891741, 2025).
tumor (7 papers, 2016 to 2025). "Interestingly, recent studies have inferred the interaction of CHIT1 with glycan substrates associated to the surface of epithelial cells and macrophages, and have implicated CHIT1 ChBD (ChBDCHIT1) in tumor metastasis of osteolytic lesions." (PMID 27111557, 2016). "By contrast, Yap1KD; Gp130FF tumor organoids showed more prominent expression of Chit1 (marker for adaptive immune responses), Cidea (apoptosis), and Inf2 (cell adhesion)." (PMID 37957015, 2024). "CCL18+M1, CXCL9+M2, and TIMP1+M3 were enriched in tumor tissues and were regarded as TAMs, whereas SELENOP+M4, MMP7+M5, CHIT1+M6, and PPARG+M7 were enriched in normal tissues and considered as resident tissue macrophages (RTMs)." (PMID 34659209, 2021). "CHIT1 is widely considered as a marker to activate macrophages, which is mainly expressed in macrophages but not in tumor cells." (PMID 36249005, 2022).
cardiovascular disease (5 papers, 2018 to 2023). "Chitinase-3-like protein 1 (CHI3L1, also known as YKL-40) and chitotriosidase (CHIT1) are proteins expressed in response to inflammation and have both been associated with cardiovascular disorders." (PMID 30311184, 2018).
cancer (4 papers, 2016 to 2022). A tumor composed of atypical neoplastic, often pleomorphic cells that invade other tissues. "In this work, we characterized two variations rs61745299 and rs35920428 within the CHIT1 gene that were associated with elevated expression levels of the C-reaction protein in the cancer tissue." (PMID 27153562, 2016). "We used the western blotting analysis to measure the expression levels of CHIT1, C reaction protein, C-myc and β-catenin genes in cancer and normal tissues in the wild and variant types of the gene." (PMID 27153562, 2016). "Like the CHIT1 gene, the expression levels of C reaction protein gene also exhibited statistically significant differences between the cancer and normal tissues in the CHIT1 gene mutant type groups." (PMID 27153562, 2016). "The expression levels of CHIT1 were higher in cancer than in normal tissues in both heterozygous and homozygous variation type groups but not in the wild type CHIT1 group." (PMID 27153562, 2016). "Western blotting analysis showed that the variations increased the expression levels of the CHIT1 and C-reaction protein genes in the cancer tissue." (PMID 27153562, 2016). "We found that two variations rs61745299 and rs35920428 within the CDS region of CHIT1 gene were associated with the risk of CRC in the Chinese Han Population, and the variations increased expression levels of the CHIT1 and C-reaction protein genes in the cancer tissue." (PMID 27153562, 2016).
neurological disorders (4 papers, 2013 to 2024). "Although CHIT-1 has also been implicated in various neurological diseases, its function in the CNS pathology remains least understood." (PMID 29246232, 2017). "The mechanisms of CHIT-1 induction in each of the neurological disorders appear to be unique to the disease." (PMID 24295388, 2013).
metabolic disease (2 papers, 2025). A congenital disorder (due to inherited enzyme abnormality) or acquired (due to failure of a metabolically important organ) disorder resulting from an abnormal metabolic process. "This indicates that CHIT1 inhibition can effectively shift metabolism towards a more energetic state, which can be beneficial for the treatment of metabolic disorders, as proven by drugs like metformin or the newly FDA-registered drug for MASH, resmetirom." (PMID 40510344, 2025).
inflammatory myopathies (1 paper, 2025). "Interestingly, a significant increase in serum CHIT1 levels was observed in mitochondriopathies compared to unaffected controls, whereas no relevant changes were observed in hereditary and inflammatory myopathies." (PMID 39891741, 2025).
neuromuscular disease (1 paper, 2025). "In conclusion, serological assessment in a large cohort of patients with neuromuscular diseases suggests that CHIT1 levels are significantly elevated in mitochondriopathies and may complement the established biomarkers FGF21 and GDF15." (PMID 39891741, 2025).
CHIT1 also shares sentences with these, for which no sentence is quoted: Bacterial Infections (2 papers); cystic fibrosis (2); endothelial dysfunction (2); inflammatory bowel disease (2); rheumatoid arthritis (2); scleroderma (2); systemic sclerosis (2); acromegaly (1); adenocarcinoma (1); amyloidosis (1); ankylosing spondylitis (1); beta thalassemia (1); brain diseases (1); breast carcinoma (1); cervical cancer (1); childhood asthma (1); chlamydia (1); chronic kidney disease (1); coronary artery disease (1); gastritis (1); glaucoma (1); Glucose intolerance (1); head and neck cancer (1); Hypertension (1); inflammation (1); liver cirrhosis (1); myeloma (1); Myelopathy (1); Niemann-Pick disease type A (1); Niemann-Pick disease type C (1).
A further 14 diseases each share a sentence with CHIT1 in 1 paper.